RNU6-166P (RNA, U6 small nuclear 166, pseudogene)
Gene: Small nuclear RNA gene on chromosome 12 (65,095,749 to 65,095,855, forward strand). Ensembl gene ENSG00000207099.
Homologues: Orthologues: chimpanzee U6 (100% identical), macaque U6 (96% identical), guinea pig U6 (88% identical), rabbit U6 (88% identical), rabbit U6 (81% identical). Paralogues in human: RNU6-41P (96% identical), RNU6-15P (95% identical), RNU6-12P (94% identical), RNU6-13P (94% identical), RNU6-25P (94% identical), RNU6-26P (94% identical), RNU6-31P (94% identical), RNU6-32P (94% identical), RNU6-44P (94% identical), RNU6-1 (93% identical), RNU6-1060P (93% identical), RNU6-17P (93% identical), and 1292 more.